EPCAM (epithelial cell adhesion molecule)
Diseases named in the same sentence as EPCAM in open-access papers (continued):
Sharing a sentence is not in itself a finding about the gene and the disease.
tumor (continued). "The CellSearch system demonstrates high efficiency in detecting tumor cells with high expression of EpCAM." (PMID 39743435, 2025). "Given the sensitivity and specificity of EpCAM‐based tumor cell identification, an initial strategy focused on EpCAM‐based positive selection." (PMID 40525275, 2025). "The results showed a pattern in which PECAM1, VWF, CXCR4, and CXCL12 appeared to infiltrate regions of the tumor delineated by HE staining and EPCAM." (PMID 39965034, 2025). "Resistant TICs display increased sphere-forming ability, higher proportions of EpCAM-positive cells, and upregulated YAP expression, all of which are associated with stemness and aggressive tumor behavior." (PMID 40568600, 2025). "employed protein splicing technology to generate an IgG-like bispecific antibody (CD3 × EpCAM BsAb) capable of binding CD3 on T cells and EpCAM on tumor cells, enabling efficient T-cell redirection and activation." (PMID 41320679, 2025). "We tested the effect of EpCAM-NIR-PIT using Ed-IR700 as the AbPC in athymic nude mice bearing MCF-7 tumours." (PMID 40792441, 2025). "For example, a bispecific antibody that simultaneously targets the tumor-specific antigen EpCAM and CD3 molecule has shown significant anti-tumor effects." (PMID 41030448, 2025). "Circulating tumor cells expressing EPCAM are potent biomarkers for distinguishing patients with TC who achieved remission after surgery from those who did not." (PMID 41551611, 2025). "Targeting IDO1 selectively has demonstrated enhanced anti-tumor effects when combined with EpCAM/CD3-bispecific antibodies in BRCA with high IDO1 expression, underscoring its clinical importance." (PMID 40061889, 2025). "This antibody is bi-specific, meaning one antigen-binding site binds T cells, and the other binds to the EpCAM marker on tumor cells." (PMID 40869256, 2025). "To be able to assess TAA expression on tumor cells specifically, we assumed all tumor cells expressed the epithelial marker EpCAM and determined the percentage of TAA expressing cells relative to the EpCAM positive population." (PMID 40358156, 2025). "This led to a 50% complete remission rate and long-term anti-tumour immunity, underscoring the potential of EpCAM-targeted NIR-PIT, especially in combination with ICI, as a promising new cancer treatment strategy." (PMID 40792441, 2025). "EpCAM (Epithelial Cell Adhesion Molecule or CD326) is an epithelial cell membrane type-I glycoprotein, highly expressed in versatile neoplasia." (PMID 39939491, 2025). "Five fully human anti-EpCAM sdAbs were identified and showed good in vitro and in vivo anti-tumor activities." (PMID 40017594, 2025). "Several reports, in agreement with our results, showed that elevated levels of EpCAM-positive EVs typically reflect an increased tumor burden and have been correlated with poorer prognosis in various cancer types, including OC." (PMID 40259212, 2025). "EpCAM, a transmembrane glycoprotein widely recognized as a “universal” tumor marker for epithelial-derived cancers, is indicative of EVs originating from malignant cells." (PMID 40259212, 2025). "Cells forming 3D structures were shown to efficiently secrete tumor EVs positive for epithelial cell adhesion molecule (EpCAM) and HSP90." (PMID 40806235, 2025). "Given the potent anti-tumor activity of EpCAM CAR-T cells in vitro, we explored their efficacy and evaluated the safety in vivo." (PMID 41417221, 2025). "So far, therapies targeting cell surface markers such as CD123, CD44v6, and EpCAM have shown promise in eliminating CSCs and reducing the potential for tumor relapse." (PMID 40868290, 2025). "The detection of the presence of tumor cells in blood using immunomagnetic enrichment targeting EpCAM introduced in 1998 initiated the development of the CellSearch system." (PMID 39743435, 2025). "To rapidly identify tumor cells in MPEs, we employed flow cytometry identification of epithelial cell adhesion molecule (EpCAM), a marker for tumor cells in MPE." (PMID 40525275, 2025).
tumor (continued). "It has been demonstrated that EpCAM+CD45+ tumor cells have heightened expression of MHC Class I antigens, allowing them to evade immune surveillance by natural killer cells." (PMID 40757000, 2025). "To bridge this gap, we included a primary HCC patient tumor sample to examine TREM1 expression in CD133+EpCAM+ LCSLCs." (PMID 40677705, 2025). "Once again, B7-H4 was more frequently coexpressed with EpCAM on tumor cells compared to CD44 on tumor cells." (PMID 38687247, 2024). "Studies have shown that EpCAM is overexpressed in a wide range of human carcinomas, including pancreas, colorectal, and prostate cancers, as well as in tumor-initiating cells." (PMID 39595576, 2024). "Seven days after tumor cell inoculation 2 × 105 EpCAM/GFPCAR T-cell were stereotactically administered into the brain parenchyma 1 mm adjacent to the tumor." (PMID 39358663, 2024). "Specifically, we observed 31 genes that were highly expressed and hypomethylated, including genes associated with tumor cell proliferation and migration, such as ATP1A1, EPCAM, TOP2A, and KIF2C." (PMID 38730618, 2024). "That the graphical representation of the frequencies of EpCAM expression among different tumor categories resulted in an S-shaped curve reflects the intense EpCAM immunostaining in the vast majority of epithelial neoplasms." (PMID 38786342, 2024). "In a mouse model of pancreatic solid tumors, CCR8-DNR-CAR-T cells targeting murine EpCAM achieved a tumor rejection rate in three out of seven mice." (PMID 39350256, 2024). "Although EpCAM is expressed with sporadic CD44v6 expression in lymphoid aggregate areas, EpCAM expression is reduced along tumor NOS2− edges." (PMID 39356141, 2024). "Tumor cells were the main population with a mean of 30% across samples and distinct from tumor-infiltrating leukocytes (TILs), which were characterized by EpCAM and CD45, respectively." (PMID 38622115, 2024). "Reports have shown that EpCAM antigen expression shows a significant upward gradient in normal cells, dysplastic epithelium and tumour tissues." (PMID 39107717, 2024). "Namely, the anti‐tumor efficacy of CAR‐engineered NK‐92 cells directed toward EpCAM and/or tumor‐specific antigens was evaluated on patient‐derived CRC organoids seeded on a Matrigel‐coated surface." (PMID 38962943, 2024). "We demonstrated that EpCAM is subjected to an intense cleavage process in ATC-derived 3D tumor spheres and that the 3D model faithfully mimics what was observed in patient's samples." (PMID 38835027, 2024). "We also confirmed the induction of high levels of MHC-II and PD-L1 on the EpCAM+ tumor epithelial cells co-cultured with IEL CD4 or CD3+ T cells." (PMID 38327516, 2024). "In solid tumors, the most commonly targeted tumor-associated antigens (TAAs) include CEA, HER2, GPC3, and EpCAM, whereas tumor-specific antigens (TSAs) are relatively rare, which significantly limits the application of CAR-T cell therapy in solid tumors." (PMID 39350256, 2024). "It has been shown that SAR-T cells, in conjunction with an anti-epithelial cell adhesion molecule (EpCAM) x anti-EGFRvIII BiAb, mediate potent cytotoxic effects upon EpCAM+ tumor cell encounter in vitro." (PMID 38887285, 2024). "Currently, for most tumours, this selection process is based on the expression of the epithelial cell adhesion molecule (EpCAM)." (PMID 38674436, 2024). "Some PD-L1 expression was observed in EpCAM+ tumor areas (yellow arrow), however most PD-L1 was present in the CD45.2+ compartments of the TME as can be seen in 20 × maginification images (white arrow)." (PMID 39009951, 2024). "A recent study utilizing a mouse model of orthotopic human HCC demonstrated that chimeric antigen receptor CAR-T cells targeting EpCAM effectively suppressed tumor growth and prolonged survival." (PMID 39417449, 2024).
tumor (continued). "Houvast and colleagues recently designed two ankyrin repeat proteins (DARPins) targeting EpCAM that have been validated for their ability to provide clear tumor delineation in preclinical models, indicating their potential for pan-carcinoma visualization." (PMID 39766041, 2024). "In previous studies, monotherapy with anti-EpCAM antibodies demonstrated limited anti-tumor efficacy, highlighting the need for a novel approach to enhance therapeutic outcomes." (PMID 39595576, 2024). "Efficient sorting and capturing of cells with different levels of EpCAM expression will help reveal the molecular basis of EpCAM heterogeneity expression, providing new biomarkers for early tumor detection and personalized therapy." (PMID 38675353, 2024). "Additional immunohistochemical analyses for tumor-related antigens such as EpCAM or mucin 1 are also needed." (PMID 38833451, 2024). "Fine‐tuning of CARs targeted to EpCAM to reduce CAR affinity toward EpCAM restricted their activity to tumor cells with high EpCAM expression." (PMID 39618102, 2024). "EPCAM is considered a key cancer stem cell regulator for cancer initiation and a marker for acquired stem cell criteria in tumor cells." (PMID 38773585, 2024). "EpCAM is also expressed on cancer stem cells (CSCs), and can contribute to tumor invasion, metastasis and treatment resistance." (PMID 39513807, 2024). "EPCAM plays a crucial role in promoting cell cycle, tumor cell proliferation, migration and immune evasion in various epithelial cancers." (PMID 40836974, 2024). "It was further shown that the EpEX-EGFR-ERK1/2 signaling axis enhanced RIP of EpCAM in order to release EpICD promoting tumor progression." (PMID 39010070, 2024). "Nonetheless, glioblastoma tumour cells exhibit a mesenchymal phenotype and, consequently, lack EpCAM expression." (PMID 38674436, 2024). "Epithelial cell adhesion molecule (EpCAM), a well-established marker for circulating tumor cells, plays a crucial role in the complex process of cancer metastasis." (PMID 38187284, 2024). "EpCAM-specific CAR-NK-92 cells showed substantial inhibition of tumor growth compared to Control-NK-92 cells." (PMID 38694508, 2024). "Metastatic tumor cells in the circulatory system are considered as circulating tumor cells (CTCs), which can be detected and captured through EpCAM, the surface marker ubiquitously and strongly expressed in epithelial cancer cells." (PMID 38791091, 2024). "In the TIMER database, the analysis revealed that EpCAM expression exhibited a noteworthy increase in various tumor types when compared to normal tissues." (PMID 38187284, 2024). "The Ki67 expression was significantly reduced in tumours injected with EpCAM-CAR-T cells compared with controls." (PMID 39107717, 2024). "The BiTE construct has been engineered to exhibit dual binding affinity for EpCAM+ tumor cells and CD3+ T cells, leading to the formation of clusters and subsequent activation of CD4+ and CD8+ T cells alongside with cancer cells." (PMID 38464532, 2024). "Circulating tumor cells (CTCs) are the most commonly isolated cells using antibody-based methods targeting the expression of epithelial adhesion molecule (EpCAM, CD326), which is crucial for the malignancy of epithelial tumors." (PMID 39519195, 2024). "EpCAM/CD326 is a multifunctional transmembrane glycoprotein that participates in tumor proliferation, metabolism, immunosuppression, treatment resistance, angiogenesis, and, last but not least, cancer stemness." (PMID 39473666, 2024). "As previously demonstrated, we observed a reduction in tumor growth after intraparenchymal injection of EpCAM/GFPCAR T-cell, which was accompanied by a survival benefit compared to GFPT-cell." (PMID 39358663, 2024). "FOLR1 expression was detected in the epithelial tumor cells of all patient samples, indicated by co-expression with EPCAM, which is a well-known marker for human epithelial tissues and carcinomas." (PMID 38254822, 2024).
tumor (continued). "In BrM, we also identified four tumor cell clusters, termed Tumor_A-D, stratified based on expression of EpCAM, cytokeratin 8, cytokeratin 14, and E-cadherin." (PMID 38622132, 2024). "Glabridin inhibits the TGF-β/SMAD2 pathway by upregulating miR-148a, reducing cancer stem cell markers (CD44, EpCAM), and impairing self-renewal, tumor sphere formation, and independent growth." (PMID 39723390, 2024). "Albeit at lower intensity, also EpCAM+ tumor areas exhibit PD-L1 expression, revealing PD-L1 expression by different cell populations throughout the TME." (PMID 39009951, 2024). "EMT is a process in which epithelial tumor cells lose their adhesion capacity due to downregulation of EpCAM expression." (PMID 39108869, 2024). "The immune and tumor epithelial ROIs were clearly separated, with distinct enrichment of epithelial (e.g., EpCAM, PanCK) and immune (CD3, CD45) cell markers, whereas mouse IgG2a antibody (negative control) showed minimal signal." (PMID 38300710, 2024). "Bispecific antibodies (BiTEs), which connect T cells to tumor cells by targeting CD3 on T cells and TAAs like EpCAM or CEA, have shown efficacy against KRAS- and BRAF-mutated CRC cells, where conventional therapies fail." (PMID 39684219, 2024). "The huKS-IL2 IC improves NK-tumor cell conjugation by exclusively targeting the EpCAM antigen expressed in lung, ovary, colon, and other adenocarcinomas." (PMID 38337114, 2024). "In contrast, others, such as EpCAM and vimentin, are present in every tumor cell and can be potentially used to detect every type of CTCs." (PMID 37874534, 2024). "In light of EpCAM's significant involvement in tumor immunity, we developed a prognostic model incorporating eight immune-related genes." (PMID 38187284, 2024). "FACS analysis further revealed an abundance of EPCAM‐low cells in the PyVT‐Ovol2KO tumor population, which is rare in PyVT‐Ovol2WT tumors." (PMID 38627980, 2024). "An anti-EpCAM x CD3 BsAb is designed to address on-target off-tumor of previous anti-EpCAM products by having reduced affinity for both targets at the pH in healthy tissue and higher affinity in the more acidic pH of the TME." (PMID 38746685, 2024). "Beyond EpCAM+ tumour cells, there's growing interest in targeting cancer stem cells (CSCs) that express CD133 due to their potential role in initiating cancer." (PMID 39472273, 2024). "In immunohistochemical examination of primary tumors, as among CTCs, the tumor cell population was heterogeneous in terms of EpCAM expression." (PMID 39456890, 2024). "Data on both EpCAM and CKpan immunostaining were available for 11,053 tumors from 101 tumor categories." (PMID 38786342, 2024). "Tumor sections were stained with antibodies to DEFA5 and epithelial cell adhesion molecule (ECad) to evaluate the integrity of tumor tissue." (PMID 38182890, 2024). "The epithelial cell adhesion molecule (EpCAM) protein is often expressed on normal epithelial cells and is overexpressed in a subset of tumor cells such as adenocarcinomas of the stomach, colon, prostate, and pancreas." (PMID 39200223, 2024). "The practicability of FOM for tumor discrimination was analyzed using vital tissue labeling with anti-EGFR AY13 or mixed anti-EpCAM 9C4/anti-CD31 WM59 mAbs." (PMID 38883274, 2024). "EpCAM serves as a well-established marker for the detection of circulating tumor cells and the identification of cancer stem cells." (PMID 38187284, 2024). "Thanks to both the tumor-specific expression pattern of EpCAM and the optimal pharmacokinetics and flexible manufacturability of DARPins, EpCAM-binding DARPins form a promising class of pan-carcinoma targeting agents." (PMID 37642704, 2024). "Next, we analyzed the spatial distribution of EpCAM/GFPCAR T-cell (± anti-PD-1/IgG antibodies) within the tumor between both experimental groups." (PMID 39358663, 2024). "This location provides an intact tumor microenvironment that allows for EpCAM expressing HCC epithelial cells to engage in cell–cell and cell–stromal interactions." (PMID 39199591, 2024).
tumor (continued). "Following FACS, CAFs were analyzed in parallel to isolated CD45+ immune and EPCAM+ tumor cells (right)." (PMID 38937629, 2024). "A potential limitation of these aptamers as cell-targeting ligands is the possibility of eliciting on-target, off-tumor effects, given that EpCAM is expressed on healthy epithelial cells." (PMID 39513807, 2024). "Our in vivo results indicate that the inhibition of HIFs by FM19G11, as well as its downstream effectors of the pathway, VEGF/VEGFR1 autocrine loop, and EGF/EGFR autocrine loop markedly reduced tumor growth as well as the expansion of the EpCAM+/ABCG2+ cells." (PMID 39963656, 2024). "Most investigations on circulating tumor cells (CTCs) have utilized methodologies designed to isolate cells expressing EpCAM." (PMID 39456890, 2024). "We cannot exclude that the lower uptake in metastases is due to the lower level of EpCAM expression in tumor cells." (PMID 39199590, 2024). "These include the antibody-mediated detection of tumor-associated antigens such as the epidermal growth factor receptor EGFR and the epithelial cell adhesion molecule EpCAM in combination with near-infrared dyes." (PMID 38390268, 2024). "An initial attempt for PET imaging of EpCAM expressing tumors was achieved in A-431 tumor-bearing athymic mice using 68Ga-labelled HBED-CC scFv429, an HBED chelated diabody." (PMID 38609981, 2024). "To date, most studies on CTCs have focused on patients with carcinomas, utilising tumour cell expression of cytokeratins such as epithelial cell adhesion molecule (EpCAM) to capture CTCs." (PMID 39802953, 2024). "During the epithelial–mesenchymal transition (EMT) process in tumor cells, epithelial markers such as the epithelial cell adhesion molecule (EpCAM) and cytokeratin (CK) are downregulated, whereas mesenchymal markers, including TWIST, are upregulated." (PMID 39199691, 2024). "Immunostaining of β‐catenin, EGFR, and EpCAM confirmed that these proteins were highly expressed in the Nr2e3−/− tumor tissues at 24‐week and 48‐week time points." (PMID 38790135, 2024). "EpCAM targeting aptamer was designed for site-specific homing of aptamer-conjugated-2c-loaded nanoparticles (Apt-2cNP) at the CRC tumor site to enhance therapeutic potential and reduce off-target toxicity in normal cells." (PMID 39164686, 2024). "In complex tumor biology, epithelial cell adhesion molecule (EpCAM) fragment patterns have the potential to reveal cancer-specific changes." (PMID 38841622, 2024). "In PDAC, for example, the identification of tumor cells often involves the use of epithelial markers (e.g., E-Cadherin or EpCAM) as well as intracellular markers such as the lineage-specific cytokeratin subtypes." (PMID 39200223, 2024). "EpCAM, typically used as a tumor biomarker, is a transmembrane glycoprotein known for its self-renewing, highly tumorigenic, and genetic stability properties." (PMID 38735927, 2024). "As expected, EpCAM knockout cells formed significantly smaller tumors and displayed reduced tumor progression compared to control cells." (PMID 39010070, 2024). "In these tumors, the apical transmembrane glycoprotein MUC1 [also known as epithelial membrane antigen (EMA)] is found at the tumor periphery, and the basolateral protein epithelial cell adhesion molecule (EPCAM) is found on the inward-facing membranes." (PMID 38465512, 2024). "One of the most important findings is that EpCAM is expressed on the surface of CSCs and circulating tumor cells, which makes the protein a potent target for therapeutics and diagnostics." (PMID 39010070, 2024). "Analysis via FISH (CEP8 and CEP17 probes) and immunofluorescence (EpCAM) detected aneuploid and tumor cells." (PMID 38952968, 2024). "FOM and labeling with PE-conjugated anti-EGFR AY13 (3-day treatment) and anti-EpCAM 9C4 (6-day treatment) mAbs identified additional CAM specimens bearing macroscopically invisible vital tumor microresidues." (PMID 38883274, 2024).